AGXT2 (alanine--glyoxylate aminotransferase 2)
Diseases named in the same sentence as AGXT2 in open-access papers:
AGXT2 is named in the same sentence as 41 diseases in open-access papers, as found by Europe PMC text mining. Sharing a sentence is not in itself a finding about the gene and the disease. The quoted sentences say what the papers report.
Hypertension (8 papers, 2014 to 2021). The presence of chronic increased pressure in the systemic arterial system. "Agxt2 deficient mice are viable and develop mild hypertension presumably due to elevation of systemic ADMA levels." (PMID 27752063, 2016). "Besides, AGXT2 has also been associated with hypertension, a major risk factors of MI." (PMID 29245966, 2017). "Considering that Agxt2 knockout (KO) mice show elevated levels of ADMA in circulation with reduced NO concentration and hypertension, it is possible that AGXT2 is a regulator of blood pressure (BP) even in humans." (PMID 33879046, 2021). "Other than the AGXT2 and DDAH1 genotypes, the following parameters were significantly associated with AST (hypertension [p = 0.029]) and ALT (age [p < 0.001], BMI [p = 0.004], DM [p = 0.005], and depression [p < 0.001])." (PMID 33879046, 2021). "Despite the fact that additional research is needed in terms of AGXT2 function in the kidney and liver, the four functional SNPs of AGXT2 and their haplotypes are useful tools for predicting hypertension, DM, and their related complications." (PMID 33879046, 2021). "Glyoxylate is a substrate of alanine-glyoxylate aminotransferase-2 (AGT2), which has been reported to be involved in the regulation of hypertension and to protect from the inhibition of NO production associated with hypertension." (PMID 24465478, 2014). "In addition, the variants of two enzymes have been shown to be associated with several vascular conditions and diseases (AGXT2: carotid atherosclerosis, atrial fibrillation and ischemic stroke, and coronary heart disease; DDAH1: hypertension and T2DM)." (PMID 33879046, 2021). "Authors of this particular study hypothesized a connection to hypertension, as glyoxylate is a substrate of alanine-glyoxylate aminotransferase-2 (AGT2), which regulates hypertension." (PMID 26636104, 2016). "Based on the data of the current study ADMA-related impairment of nitric oxide synthases has become an unlikely (but still not impossible) explanation and alternative AGXT2 substrates should be explored as possible mediators of hypertension associated with AGXT2 SNPs." (PMID 24586340, 2014). "Missense variants of AGXT2, but not DDAH1, may be related to vulnerability to vascular diseases such as hypertension and DM via the NO system." (PMID 33879046, 2021).
diabetes (4 papers, 2016 to 2024). "AGXT2 single-nucleotide polymorphisms (SNPs) are related to systemic diseases [coronary artery disease, carotid atherosclerosis, chronic heart failure, diabetes mellitus (DM), and mild cognitive impairment] and biological parameters [blood pressure, sugar, and creatinine]." (PMID 38261033, 2024). "Specifically, we show that db/db mice, an established model of hepatic steatosis and diabetes, have increased protein and specific activity levels of AGXT2 in the liver and kidney." (PMID 39660051, 2024).
atrial fibrillation (3 papers, 2016 to 2024). A disorder characterized by an electrocardiographic finding of a supraventricular arrhythmia characterized by the replacement of consistent P waves by rapid oscillations or fibrillatory waves that vary in size, shape and timing and are accompanied by an irregular ventricular response. "Based on NCBI, T09B4.8 is similar to human AGXT2, and mutations in AGXT2 may contribute to the development of atrial fibrillation and age-related thromboembolic complications." (PMID 38248852, 2024). "In addition, it has been shown that high ADMA levels in plasma/serum are relevant to the exaggerated BP response to exercise, congestive heart failure, and coronary atherosclerosis, and the AGXT2 genotypes are associated with atrial fibrillation and ischemic stroke and coronary heart disease." (PMID 33879046, 2021).
chronic kidney disease (3 papers, 2015 to 2024). Impairment of the renal function secondary to chronic kidney damage persisting for three or more months. "Within the GWAS Catalog, 16 GWAS studies identified 22 associations of AGXT2 with chronic kidney diseases using urinary metabolite measurements." (PMID 37610350, 2023). "Results showed that approximately one third of the cats with the AA variant of the AGXT2 gene have stones, that chronic kidney disease (CKD) is more common in cats with stones, and that having stones results in a shorter lifespan." (PMID 39457388, 2024).
coronary heart disease (3 papers, 2017 to 2023). "Last but not least, candidate gene study in the attempt to associate AGXT2 polymorphism with coronary heart disease also showed a positive result, although with a low statistical power and no subsequent functional studies." (PMID 29245966, 2017).
endothelial dysfunction (3 papers, 2022 to 2024). In vascular diseases, endothelial dysfunction is a systemic pathological state of the endothelium (the inner lining of blood vessels) and can be broadly defined as an imbalance between vasodilating and vasoconstricting substances produced by (or acting on) the endothelium. "AGXT2 impacts the nitric oxide (NO) pathway through the competitive inhibition of NOS by ADMA; as a result, AGXT2 can regulate blood pressure and be related to endothelial dysfunction leading to cardiovascular disease." (PMID 38261033, 2024). "In the second part of the manuscript, we were able to demonstrate that overexpression of AGXT2 restores physiological levels of ADMA and protects from endothelial dysfunction in DDAH1 deficiency." (PMID 35672381, 2022). "Moreover, the overexpression of AGXT2 protects against asymmetric dimethylarginine-induced endothelial dysfunction and aortic remodeling." (PMID 38790162, 2024). "We crossed AGXT2 TG mice with DDAH1 knockout mice and observed that upregulation of AGXT2 lowers plasma ADMA and pulse pressure and protects the mice from endothelial dysfunction and adverse aortic remodeling." (PMID 35672381, 2022). "To test this hypothesis we generated and characterized AGXT2 transgenic mice and determined, whether this transgene can protect Ddah1 knockout mice from ADMA elevation, endothelial dysfunction and aortic remodeling." (PMID 35672381, 2022).
ischemic stroke (3 papers, 2015 to 2021). A stroke disorder caused by obstruction of blood flow to the brain, due to thrombotic (local blood clot formation) or embolic (due to a blood clot or other material traveling from another site) event. "We found strong evidence that the AGXT2 p.V498L polymorphism is associated with both paroxysmal and chronic forms of AF in coronary angiographic patients without structural heart disease in ultrasound, and earlier age at onset of ischemic stroke in patients undergoing exercise stress testing." (PMID 26984639, 2016). "We examined whether the two functional AGXT2 variants are associated with ischemic stroke and its subtypes in the meta-analysis of WTCCC2 ischemic stroke cohorts." (PMID 26984639, 2016).
acute kidney injury (2 papers, 2014 to 2023). Sudden and sustained deterioration of the kidney function characterized by decreased glomerular filtration rate, increased serum creatinine or oliguria. "Considering that plasma SDMA concentrations are linked to adverse events in cardiovascular diseases and renal failure polymorphisms within the AGXT2 gene could have further implications in disease progression and require further investigations." (PMID 24586340, 2014).
atherosclerosis (2 papers, 2019 to 2025). A disease characterized by the build-up of fatty material and calcium deposition in the arterial wall resulting in partial or complete occlusion of the arterial lumen. "However, another study presented a potentially protective effect of BAIBA on atherosclerosis, cancelling out the risk associated with elevated levels of SDMA in individuals with the AGXT2 defect." (PMID 40422899, 2025).
pulmonary hypertension (2 papers, 2015 to 2021). Increased pressure within the pulmonary circulation due to lung or heart disorder. "Therefore, we selected 16 single nucleotide polymorphisms in NOS3, DDAH1, DDAH2, AGXT2, ARG1, ARG2, and PRMT1 genes and studied their associations with dimethylarginine concentrations and the incidence of high-altitude pulmonary hypertension as well as acclimatization to high altitude." (PMID 34945057, 2021). "We found four genes to be significantly associated with high-altitude pulmonary hypertension (i.e., estimated mPAP ≥ 30 mm Hg) after adjustment for multiple testing: NOS3 rs2070744 (p = 0.003), ARG2 rs3742879 (p = 0.003), DDAH1 rs233122 (p = 0.004), and AGXT2 rs37369 (p = 0.003)." (PMID 34945057, 2021).
type 2 diabetes (2 papers, 2016). "The current findings therefore suggest an intriguing link between type 2 diabetes and AGXT2-mediated impairment of methylarginine, NO and lipid metabolism." (PMID 27752141, 2016).
AL amyloidosis (1 paper, 2021). AL Amyloidosis is a plasma cell disorder characterized by the aggregation and deposition of insoluble amyloid fibrils derived from misfolding of monoclonal immunoglobulin light chains usually produced by a plasma cell tumor. "The role of AGXT2 in renal function is worthy of further investigations especially in AL amyloidosis, as maybe it had something to do with the occurrence and development of the AL amyloidosis." (PMID 34885818, 2021).
Alzheimer disease (1 paper, 2022). A progressive, neurodegenerative disease characterized by loss of function and death of nerve cells in several areas of the brain leading to loss of cognitive function such as memory and language. "Gene-based analyses implicated AGXT2 and CALN1 for VL, while analyses of protein-protein interactions implicated synaptic proteins previously associated with Alzheimer disease biology, SYT9 and NRXN1 for VSTM; ZFAND5, GRIK2, and ZC3H18 for VL; and PRLHR for paragraph recall." (PMID 35974141, 2022).
autoimmune disease (1 paper, 2022). A disorder resulting from loss of function or tissue destruction of an organ or multiple organs, arising from humoral or cellular immune responses of the individual to their own tissue constituents. "In the case of autoimmune diseases caused by uncontrolled expansion of Teff due to TGFβ deficiency, our data suggest that AGXT2 inhibitors may suppress inflammation as our data show T cells are dependent on these two signals to survive in vivo." (PMID 35990633, 2022).
diabetic nephropathies (1 paper, 2024). "In UK-ROI, AGXT2-rs71615838 and SURF1-rs183853102 were associated with diabetic nephropathies, and TFB1M-rs869120 with eGFR." (PMID 38858654, 2024).
dihydropyrimidinase deficiency (1 paper, 2025). "Notably, AGXT2 and DPYS are involved in pyrimidine catabolism and are known markers of dihydropyrimidinase deficiency." (PMID 41228357, 2025).
fatty liver (1 paper, 2024). "SDGV is a biomarker of liver fat and its increase in hepatic steatosis results from the upregulation of AGXT2 activity." (PMID 39660051, 2024).
fatty liver disease (1 paper, 2024). A reversible condition wherein large vacuoles of triglyceride fat accumulate in liver cells via the process of steatosis. "Of interest, a recent study in a human cohort revealed a likely pathogenic role for AGXT2 in fatty liver disease." (PMID 39660051, 2024). "In a murine model of fatty liver disease, protein levels and activity of alanine:glyoxylate aminotransferase 2 (AGXT2), which produces SDGV, were increased and coincided with elevation of SDGV concentrations." (PMID 39660051, 2024).
Hyperoxaluria (1 paper, 2022). Increased excretion of oxalates in the urine. "In another report, AGXT2-/- mice exhibited hyperoxaluria and crystalluria and half of the male mice in mixed genetic background developed calcium oxalate urinary stones." (PMID 35990633, 2022).
myocardial infarction (1 paper, 2021). Gross necrosis of the myocardium, as a result of interruption of the blood supply to the area, as in coronary thrombosis. "Both SREBF chaperone (SCAP) and alanine--glyoxylate aminotransferase 2 (AGXT2) genes are responsible for cholesterol metabolism and nitric oxide (NO) production, and they are associated with premature myocardial infarction (MI)." (PMID 34445123, 2021).
Nephropathy (1 paper, 2025). A nonspecific term referring to disease or damage of the kidneys. "AGXT2 plays a pivotal role in kidney diseases, with its loss of function accelerating nephropathy progression." (PMID 39968673, 2025).
paroxysmal AF (1 paper, 2016). "In contrast to the AGXT2 SNPs, the 4q25 variant showed a stronger association with chronic AF than paroxysmal AF in both the whole study population and when excluding the patients with structural heart disease." (PMID 26984639, 2016). "When excluding the patients with structural heart disease from the analysis, a highly significant association for AGXT2 rs16899974 was observed with any AF (P = 3.9 × 10−8), and with paroxysmal AF (P = 3.0 × 10−5) and chronic AF (P = 7.0 × 10−4) separately." (PMID 26984639, 2016). "Whether the AGXT2 variants could predict the presence of a silent or paroxysmal AF in patients with acute cryptogenic ischemic stroke warrants further investigation." (PMID 26984639, 2016). "Neither of the AGXT2 variants was associated with ADMA or eGFR in any of the AF status groups; however, rs16899974 showed a borderline significant association with ADMA in patients with paroxysmal AF (P = 0.057)." (PMID 26984639, 2016).
primary hyperoxaluria type 1 (1 paper, 2019). A rare disorder of glyoxylate metabolism characterized by the accumulation of oxalate due to a deficiency of the peroxisomal hepatic enzyme L-alanine: glyoxylate aminotransferase (AGT). "However, it has been shown that only the deficiency of AGXT1, but not of AGXT2, leads to primary hyperoxaluria type I in humans, suggesting that AGXT1, but not AGXT2, plays the major role in glyoxalate detoxification." (PMID 31533264, 2019).
renal carcinoma (1 paper, 2019). A carcinoma arising from the epithelium of the renal parenchyma or the renal pelvis. "In addition, immunohistochemistry staining in The Human Protein Atlas database showed that the expression of EHHADH, ACADM and AGXT2 proteins were also significantly lower in renal carcinoma compared to normal kidney." (PMID 31839812, 2019).
Stroke (1 paper, 2016). Sudden impairment of blood flow to a part of the brain due to occlusion or rupture of an artery to the brain. "Therefore, we considered that the two functional AGXT2 variants may serve as naturally occurring genetic models to study the role of AGXT2 in human AF and its thromboembolic complications, i.e. stroke and its subtypes." (PMID 26984639, 2016).
kidney disease (7 papers, 2019 to 2025). "Dimethylarginines (SDMA and ADMA) are metabolized in liver and kidney mitochondria by alanine-glyoxylate aminotransferase 2 (AGXT2) with several links to the pathogenesis of cardiovascular and renal disease." (PMID 41075794, 2025). "Our results confirm previously identified associations of NEMG (NAT8, GATM, SLC22A2, WDR72, NOS3, AGXT2 and CPS1) with kidney disease and kidney function, providing new information that expands these associations to other kidney disease biomarkers." (PMID 38858654, 2024). "AGXT2 metabolizes ADMA to ADGV (asymmetricα-keto-dimethylguanidinovaleric acid) which later can be excreted and decreased AGXT2 enzyme activity causes ADMA accumulation, leading to renal disease development." (PMID 36735737, 2023). "It was reported that AGXT2 may play a part in the progression of renal diseases through affecting ADMA (Asymmetric dimethylarginine)/SDMA (symmetric dimethylarginine) level." (PMID 34885818, 2021).
cardiovascular disease (5 papers, 2014 to 2024). "Collectively, we hypothesize that the loss of AGXT2 function induces elevated SBP and DBP through the dysregulation of the NOS/ADMA pathway, which means that we can estimate the risk of cardiovascular diseases by detecting AGXT2 SNPs." (PMID 33879046, 2021). "AGXT2 metabolizes both ADMA and SDMA, and lower AGXT2 activity is associated with higher risk for cardiovascular disease and increased carotid intimal medial thickness." (PMID 37383439, 2023).
tumor (4 papers, 2019 to 2025). "Three hub genes (EHHADH, ACADM and AGXT2) were met the criterion of both WGCNA and PPI networks analysis, which showed highest negative association with pathological T stage (r = - 0.45, p = 0.01) and tumor grade (r = - 0.45, p = 0.01)." (PMID 31839812, 2019). "Ultimately, AGXT2, DPYS, and TNFSF8 were selected as HCC-specific epigenetic–transcriptomic gene markers that reflect significant differences in the tumor microenvironment, exhibiting distinct cell type specificity." (PMID 41228357, 2025). "Consistently, all the six DEGs (GLS2, ASS1, FOLH1B, AGXT2, CPS1, and GPT2) enriched in “arginine biosynthesis” in our results were significantly downregulated in tumor hepatic tissue from HBV-infected patients compared with adjacent nontumor tissues." (PMID 32775402, 2020). "Therefore, EHHADH, ACADM and AGXT2 could be suggested as protective tumor suppressors for ccRCC." (PMID 31839812, 2019).
metabolic disease (2 papers, 2016 to 2019). A congenital disorder (due to inherited enzyme abnormality) or acquired (due to failure of a metabolically important organ) disorder resulting from an abnormal metabolic process. "AGXT2 (alanine-glyoxylate aminotransferase 2), a multifunctional mitochondrial aminotransferase, has diverse functions in cellular physiology and its products and substrates are biomarkers of renal, cardiovascular and metabolic diseases." (PMID 31839812, 2019). "However, despite the growing evidence that AGXT2 and its substrates may play an important role in the pathogenesis of cardiovascular and metabolic diseases, the mechanisms of regulation of AGXT2 expression and activity are still unknown." (PMID 27752141, 2016).
AGXT2 also shares sentences with these, for which no sentence is quoted: dyslipidemia (2 papers); Insulin resistance (2); Obesity (2); cancer (1); congestive heart failure (1); coronary atherosclerosis (1); COVID-19 (1); depression (1); iminoglycinuria (1); Mild Cognitive Impairment (1); musculoskeletal diseases (1); renal failure (1).